ID1 (inhibitor of DNA binding 1)
Diseases named in the same sentence as ID1 in open-access papers (continued):
Sharing a sentence is not in itself a finding about the gene and the disease.
glioblastoma (continued). "In stark contrast to Id1–3, Id4 correlates with survival of glioblastoma patients by decreasing MMP2 expression, a secreted proteinase key for brain tumor invasion, via a direct inhibitory interaction with the bHLH TF Twist1." (PMID 34302526, 2022). "CBD also led to a downregulation of the sex-determining region Y (SRY)-Box 2 (Sox-2), a critical determinant of glioma tumour initiating cell growth and downstream target of Id-1, in glioblastoma cells." (PMID 35277658, 2022). "NAMPT is the rate-limiting enzyme in the NAD salvage pathway, and E2F2 acts downstream of NAMPT and controls ID1 gene transcription to drive glioblastoma CSC self-renewal." (PMID 34476219, 2021). "ID1 regulates multiple tumor-promoting pathways, such as invasiveness and self-renewal in glioblastoma." (PMID 33987093, 2021). "PPM1G is also involved in dephosphorylating the translation initiator 4E-BP1, thereby inhibiting the translation of its targets, such as Id1 in glioblastomas." (PMID 34290239, 2021). "A recent study reported that ID1 acted as a transcriptional regulator and played a critical role for glioblastoma initiation and chemoresistance, and ID1 knockdown promoted the treatment effect of temozolomide, delays tumor recurrence, and prolongs survival." (PMID 32596316, 2020). "In glioblastoma, ID1 knockdown in a mouse xenograft model impairs cell invasion and thereby results in increased overall survival." (PMID 31602000, 2019). "Previous studies showed that COX-2-derived PGE2 induced Id1-dependent radiation resistance and self-renewal in experimental glioblastoma." (PMID 30862036, 2019). "COX-2-derived PGE2 induced Id1-dependent radiation resistance and self-renewal in experimental mouse glioblastoma." (PMID 30862036, 2019). "USP1 is known to stabilize ID1 proteins, thereby preserving stem-cell traits in osteosarcoma and glioblastoma." (PMID 30918246, 2019). "Increase in the phosphorylation state of 4E-BP1 results in the activation of Id1 translation, leading to increased Id1 expression and glioblastoma malignancy." (PMID 28122577, 2017). "In glioblastoma cells Id1 expression is also PI3K-dependent through the phosphorylation of 4E-BP1 via Akt-mTORC1 or Akt-PPM1G." (PMID 28122577, 2017). "In metastatic breast cancer, glioblastoma and salivary gland cancer cannabidiol, a low toxic cannanbinoid, has been shown to reduce Id1 expression, resulting in less tumor growth, aggressiveness and metastasis." (PMID 28122577, 2017). "While defining the precise mechanism by which Id1 influences angiogenesis in glioblastoma is beyond the scope of this current study, some studies suggest potential factors involved in this process." (PMID 24659686, 2014). "Overall, these data suggest that the limitation of purine synthesis, limits the proliferative capacity of glioblastoma cells, and that purine salvage and the restoration of purine nucleotide concentrations rescues ID-1-KO cells to levels similar to their ID-1 intact counterparts." (PMID 39455562, 2024). "Similarly, the inhibition of Src with Dasatinib, Saracatinib, PP2 or TAT-Cx43266-283 promotes a reduction in the expression of the inhibitor of differentiation-1 (Id1) and Sox2, with the subsequent reversion of stemness in human glioblastoma stem cells." (PMID 36217026, 2022). "Since microvascular proliferation is a hallmark of greater malignancy and a cardinal feature of glioblastomas, we were interested in determining whether COX-2 or Id1 overexpression will lead to increased angiogenesis." (PMID 24659686, 2014). "Glioblastoma invasive ability has also been associated with certain angiogenic regulators linking these different phenotypes that are positively altered by COX-2 and Id1." (PMID 24659686, 2014). "This work suggests that high Id1 levels may correlate with aggressive behavior and poor prognosis in glioblastoma patients." (PMID 24659686, 2014). "More recently, several groups have demonstrated links between glioblastoma malignancy and Id1." (PMID 24659686, 2014).
glioblastoma (continued). "ID1 upregulation also abrogates differentiation signals in GSCs and contributes to temozolomide resistance in glioblastoma (GBM)." (PMID 36359776, 2022). "Id1 serves as a main mediator that abrogates differentiation signals in glioblastoma stem cells (GSCs) and contributes to GBM initiation and chemoresistance in GBM." (PMID 32410828, 2020). "Therefore, ID1 is a potential prognostic indicator and therapeutic target in glioblastomas." (PMID 24137437, 2013). "According to studies, CBD downregulate the metastatic factor (ID1) and up-regulates the pro-differentiation factor (ID2), which results in a significant reduction in the invasion glioblastoma (GBM), inhibition of GBM dispersal ex vivo, and reduction in tumor growth and Id-1 expression in vivo." (PMID 36568260, 2022). "Thus, ID1 inhibition could re-establish differentiation in glioblastoma." (PMID 35814409, 2022). "It is interested that ID1 regulates Wnt and SHH signaling in glioblastoma stem cells by suppressing CULLIN3 ubiquitin ligase." (PMID 33834612, 2021). "In GBM cells, Id1 is also a potential downstream effector of protein tyrosine kinase 7(PTK7) and transglutaminase 2 (TGM2) which are highly expressed in CD44-high glioblastoma and predicts unfavorable prognosis." (PMID 32410828, 2020). "Taken together, our results demonstrate a subpopulation of quiescent GSCs in glioblastoma, and show that GSC quiescence and activation are mediated by BMP and TGF-β signaling, through the downstream targets, ID1 and p21." (PMID 31602000, 2019). "Western blotting showed that CD133, ALDH1, NANOG, ID1 and ID3 were downregulated in U251 and T98G glioblastoma cells upon ONC201 treatment at 72 h." (PMID 28767654, 2017). "While further research is required to detail the interactions between ID-1 regulation, AMPK signaling, and metabolic reprogramming in glioblastoma cells, our data suggests that reprogramming of 1-C mediated purine synthesis plays a role in glioblastoma cell proliferation and treatment resistance." (PMID 39455562, 2024). "Instead, TGFβ does not induce ATF3 in glioblastoma multiforme, which turns the TGFβ-mediated transcription of Id1 from repression to activation." (PMID 28122577, 2017).
melanoma (27 papers, 2004 to 2024). A malignant, usually aggressive tumor composed of atypical, neoplastic melanocytes. "Another interesting category is that of circadian rhythm, whose biology frequently involves translational control for temporal expression patterns, such as melanoma antigen-encoding gene D1 (Maged1) and inhibitor of DNA binding 1 (Id1)." (PMID 33472078, 2021). "Coordinate expression of Id1 or Id3 or CD44 with HAS2 or HAS3 or CD44 was found to be associated with reduced survival of human melanoma patients." (PMID 30297743, 2018). "Still, strong ID1 expression indicated a more aggressive melanoma phenotype, and was found to be associated with increased tumour thickness, primary tumours located on the trunk, and a tendency towards increased tumour cell proliferation by Ki-67 expression." (PMID 16189525, 2005). "In the context of melanoma, overexpression of ID1 leads to systemic immunosuppression by negatively regulating key molecules involved in DC differentiation." (PMID 39676870, 2024). "In TME, IL‐1β activating suppressor of mothers against decapentaplegic/DNA‐binding 1 protein inhibitor, the Smad/ID1 signaling pathway ensures maintenance of the stemness traits of melanoma cells, thus acting as a promoter of tumor relapse and metastasis." (PMID 38775220, 2024). "In advanced melanoma, Id1 upregulation through tumor growth factor β (TGF-β) has been shown to promote the differentiation of dendritic cells (DCs) to myeloid-derived suppressor cells (MDSCs) and to suppress CD8+ T-cell proliferation." (PMID 37841258, 2023). "HA/CD44 interactions with bone morphogenetic protein (BMP) promote BMP4/7-dependent Id1/3 protein expression in melanoma, contributing to reduced survival in melanoma patients." (PMID 35154001, 2021). "HA promotes BMP4/7-dependent Id1/3 protein expression in melanoma cells by binding its cellular receptor CD44 and directly aids in cell proliferation, motility, invasion and metastasis." (PMID 32899370, 2020). "Other groups have also shown that Inhibitor of Differentiation-1 (ID1) is upregulated in DCs by melanoma-derived TGF-β, shunting DCs to differentiate toward an immature MDSC population." (PMID 31921140, 2019). "We therefore conclude that the CD44/HA axis can potentiate the ability of BMP4/7 to activate Id1 and Id3 expression in melanoma cells, thereby contributing to poor prognosis." (PMID 30297743, 2018). "Our results suggest that HA-CD44 interactions with BMPR promote BMP4/7-dependent Id1/3 protein expression in melanoma, contributing to reduced survival in melanoma patients." (PMID 30297743, 2018). "Our study reports a novel functional link between HA-CD44 interaction and BMP-induced Id1 and Id3 protein in melanoma." (PMID 30297743, 2018). "In this study we found that depletion of endogenously-produced HA by hyaluronidase treatment or by inhibition of HA synthesis by 4-methylumbelliferone (4-MU) resulted in reduced BMP4/7-dependent Id1/3 protein expression in mouse melanoma B16-F10 and Ret cells." (PMID 30297743, 2018). "Consistently, increased Id1 expression has been correlated with tumor progression and poor prognosis in malignant melanoma patients." (PMID 30297743, 2018). "To establish the translational significance of our in vivo and in vitro findings, we measured the mRNA expression of ID1 in CD11B+ cells isolated using magnetic beads from PBMC of patients with advanced melanoma (stage IV) and healthy age-matched controls." (PMID 25924227, 2015). "ID-1 overexpression has been found in several types of primary human cancers including breast, pancreatic, prostate, nasopharyngeal, melanoma and cervical cancers." (PMID 19002177, 2008). "Regarding malignant melanoma, ID1 mRNA expression, assessed by in situ hybridisation, has been associated with loss of p16 protein in melanoma in situ." (PMID 16189525, 2005). "In conclusion, our study supports a significant role of the ID1 protein in melanoma progression and patient prognosis." (PMID 16189525, 2005).
melanoma (continued). "In melanoma, a recent study suggested a role of ID1 in regulating p16 expression in some early tumours." (PMID 16189525, 2005). "In conclusion, our study suggests a significant role of ID1 protein in melanoma progression and survival." (PMID 16189525, 2005). "Increased expression was significantly associated with increased tumour thickness, and strong expression of ID1 was found significantly more frequent in primary melanomas located on the trunk, compared with other sites (χ2 test, P=0.001)." (PMID 16189525, 2005). "In invasive melanomas, ID1 mRNA positivity was limited to the in situ component and perivascular tumour areas." (PMID 16189525, 2005). "Id-1 overexpression has been found in several types of primary human cancers including breast, pancreatic, prostate, melanoma and cervical cancers." (PMID 15026801, 2004). "Id-1 plays a role in the early step of human carcinogenesis, for example, in melanoma and cervical cancer, whereas id-1 expression is markedly different between in situ and invasive breast carcinoma." (PMID 15026801, 2004). "In this study, our data indicate the IL-1β stimulation could enhance the stemness of HNSCC and melanoma cells through activating Smad1/5/8 and ID1 signaling pathway." (PMID 32547321, 2020). "In other types of cancer than melanoma, ID1 showed promise as a prognostic marker for OS." (PMID 31953577, 2020). "Interestingly, it was found in melanoma mouse models that tumor cells through TGF-β production can promote MDSC formation by induction of the transcriptional regulator called inhibitor of differentiation 1 (ID1)." (PMID 31953577, 2020). "Additionally, ID1 mRNA levels in CD11b+ myeloid cells from peripheral blood mononuclear cells (PBMC) of melanoma patients were increased in comparison to those from healthy donors." (PMID 31953577, 2020). "ID1 expressing cells in melanoma patients have an immunosuppressive phenotype." (PMID 31953577, 2020). "Moreover, expression of ID1 in monocytes significantly decreased in PBMC samples taken after surgical removal of melanoma metastases, compared to those taken before surgery." (PMID 31953577, 2020). "A highly significant elevation of ID1 was observed in CD33+CD11b+CD14+HLA-DRlow monocytic MDSC in the blood of melanoma patients compared to their HLA-DRhigh counterparts, while expression of ID1 correlated positively with established MDSC markers S100A8/9 and iNOS." (PMID 31953577, 2020). "In conclusion, our study demonstrated that IL-1β could enhance the stemness of squamous cell carcinoma and melanoma via activating Smad/ID1 pathway." (PMID 32547321, 2020). "We therefore investigated whether HA in the pericellular matrix might play a similar role in regulating BMP-induced Id1/Id3 expression in B16-F10 and Ret melanoma cells." (PMID 30297743, 2018). "Here we report that HA promotes BMP4/7-dependent Id1/3 protein expression in melanoma cells." (PMID 30297743, 2018). "To further substantiate the notion that HA promotes BMP4/7-induced Id1/Id3 expression in melanoma cells, we treated the cells with 4-MU, a 7-hydroxy-4-methylcoumarin that inhibits HA synthesis by depleting cellular UDP-glucuronic acid and downregulating HA synthase expression." (PMID 30297743, 2018). "Next we determined whether CD44, the principal cell surface receptor for HA, plays a role in the ability of HA to stimulate BMP-induced Id1 and Id3 expression in B16-F10 and Ret melanoma cells." (PMID 30297743, 2018). "Increased BMP-induced Id1/Id3 expression in response to HA could act at a number of levels to promote melanoma formation and progression." (PMID 30297743, 2018). "In this study, we investigated this hypothesis, and found that the CD44/HA axis fosters BMP4/7-dependent Id1/3 protein expression in melanoma cells through interactions between CD44 and BMPR." (PMID 30297743, 2018).
melanoma (continued). "The tumor-promoting properties of these transcriptional regulators, and the ability of the HA/CD44 axis to promote their expression in response to BMP stimulation, likely underlies the association between coordinate expression of Id1/Id3 and HAS2/HAS3/CD44, and reduced survival of melanoma patients." (PMID 30297743, 2018). "In melanoma, the Id1-induced up-regulation of MMP2 is mediated by the adhesion molecule MUC18." (PMID 28122577, 2017). "The influence of MK615, an extract from the Japanese apricot “Prunus mume” known for antitumorigenic and antiinflammatory effects, has been studied in human malignant melanoma cells: MK615 reduces Id1 expression and, therefore, cell growth through the inhibition of the ERK1/2 pathway." (PMID 28122577, 2017). "Because of its potent regulatory control of angiogenic and vasculogenic processes, it was not surprising to find that Id1 acts as a negative transcriptional regulator for proteins associated with malignant melanoma development." (PMID 27071670, 2016). "Furthermore, advanced melanoma patients have increased plasma TGFβ levels and express higher levels of ID1 in myeloid peripheral blood cells." (PMID 25924227, 2015). "On the other hand, strong ID1 expression was associated with thicker primary tumours and presence of BRAF mutations, as well as with significantly reduced patient survival, indicating an important role in melanoma progression." (PMID 16189525, 2005). "The absence of correlation with p16 protein expression and angiogenesis suggests that other regulatory pathways and mechanisms might be influenced by ID1 in melanomas." (PMID 16189525, 2005). "Inhibitor of differentiation 1 (ID1) is a transcriptional regulator that was shown to be centrally involved in the induction of immunosuppressive properties in myeloid cells in mice, while it was overexpressed in CD11b+ cells in the blood of late-stage melanoma patients." (PMID 31953577, 2020). "TBX3 directly promotes the expression of Inhibitor of DNA binding 1 (ID1), a key regulator of tumor progression, and inhibits E-cadherin expression via the TBX3-ID1-MITF-axis, promoting migration and invasiveness of melanoma cells." (PMID 38965548, 2024). "In melanoma tumors, TGF-β mediated inhibitor of differentiation 1 (Id1) upregulation skews dendritic cell differentiation to MDSCs and mobilizes VEGFR1+ haematopoietic progenitor cells (HPCs) during PMN formation." (PMID 30792719, 2019). "Hyaluronidase pre-treatment reduced Id1/3 protein expression in response to BMP4 and BMP7 in both melanoma cell lines by around 50%." (PMID 30297743, 2018). "MUC18 positively regulates Id1 expression through the modulation of ATF3, contributing to melanoma metastasis." (PMID 28122577, 2017). "In this report, we show that melanoma cells upregulate ID3 expression (and also ID1 and ID2) in response to vemurafenib (or to the combination vemurafenib + trametinib) in vitro and in patients’ tumors." (PMID 29299138, 2017). "When the expression of CD146 was rescued in CD146–knockdown melanoma cells, Id-1 expression was increased, and ATF-3 expression was reduced, which showed that both Id-1 and ATF-3 were specifically regulated by CD146." (PMID 25685061, 2015). "Lungs from Id1-overexpressing and control vector-transplanted mice were analysed for metastatic tumour burden by quantification of mCherry-labelled B16F10 melanoma cells." (PMID 25924227, 2015). "It has also been shown that CD146 contributes to human melanoma cell invasion through the regulation of MMP-2 transcription and protein expression via Id-1." (PMID 25685061, 2015). "More importantly, we demonstrate that in melanoma patients, plasma levels of TGFβ and myeloid PBMC Id1 levels are both significantly upregulated." (PMID 25924227, 2015).
melanoma (continued). "The purpose of our present study was to examine the possible regulatory role of ID1 and ETS transcription factors in melanoma progression, especially since they are known to influence both the CDKN2A/p16 pathway and angiogenesis regulation." (PMID 16189525, 2005). "Therefore, we comprehensively assessed ID1 expression in PBMC from stage III and IV melanoma patients, and studied ID1 regulation in models for human monocyte differentiation towards monocyte-derived dendritic cells." (PMID 31953577, 2020). "Targeting Id1 and Id3 protein expression by perturbation of the HA-CD44 interaction might be a promising and effective approach for melanoma therapy." (PMID 30297743, 2018). "Moreover, knockdown of ID1 could abrogate IL-1β stimulation-prompted stem cell-like properties of HNSCC and melanoma cells." (PMID 32547321, 2020). "Given that the CD44/HA axis promotes BMP signalling in chondrocytes, and the correlation between these factors and poor prognosis in melanoma, we hypothesized that HA might promote BMP4/7-dependent Id1/3 protein expression in melanoma cells in CD44-dependent manner." (PMID 30297743, 2018). "In addition, if disseminating melanoma cells settle in an HA-rich microenvironment with only low concentrations of BMPs, then melanoma metastasis formation may be fostered by HA-stimulated BMP-induced Id1/Id3 expression due to the tumor-initiating properties endowed on cancer cells by Id1 and Id3." (PMID 30297743, 2018).